MIR5584 (microRNA 5584)
Synonyms: hsa-mir-5584
Gene: MicroRNA gene on chromosome 1 (44,545,493 to 44,545,552, forward strand). Ensembl gene ENSG00000263381.
Homologues: Orthologues: chimpanzee MIR5584 (100% identical).